FDX1 (ferredoxin 1)
Diseases named in the same sentence as FDX1 in open-access papers (continued):
Sharing a sentence is not in itself a finding about the gene and the disease.
tumor (167 papers, 2013 to 2026). "Under the action of ferredoxin-1 (FDX1), it induces abnormal aggregation of lipoylated proteins and loss of iron-sulphur clusters, thereby generating protein toxicity stress and killing tumor cells." (PMID 42072452, 2026). "Nevertheless, our results fully confirmed that FDX1 exhibited a low-expression pattern in ccRCC, and its reduced expression was associated with higher tumor stages and grades." (PMID 40118855, 2025). "In the TCGA cohort, among the 10 cuproptosis-related genes associated with tumor and normal tissues, only FDX1 was downregulated in HCC tissues, while the expression levels of the other genes were upregulated." (PMID 40064873, 2025). "The results also indicated that FDX1 expression was markedly decreased in ccRCC and that reduced FDX1 expression was associated with higher tumor stage, grade, lymph node invasion, and distant metastasis (T3/T4, G3/G4, Stage III/IV, N1, and M1)." (PMID 40118855, 2025). "Previous studies have shown that tumor cells with high FDX1 expression exhibit increased more susceptibility to cuproptosis under equivalent copper concentrations." (PMID 40630211, 2025). "This reveals an independent function of FDX1 as a tumor-intrinsic immunity activator linked to mitochondrial stress signaling." (PMID 41199656, 2025). "FDX1 (ferredoxin 1), as a core regulator of cuproptosis, is closely associated with tumor cell activity and immune response." (PMID 40276654, 2025). "The results of our pathway analysis demonstrated that the relation between FDX1 expression level and classical tumor-associated pathways and immune-associated pathways is complex and related to tumor types." (PMID 37193786, 2023). "Further analysis demonstrated a significant correlation between FDX1 expression and immune cell infiltration, tumor mutational burden (TMB) score, microsatellite instability (MSI) score and drug sensitivity." (PMID 37505170, 2023). "We further explored reasons of FDX1-caused survival difference from the cuproptosis pathway and tumor immune microenvironment change using HCC samples and hepatic tumor cells." (PMID 37361595, 2023). "The relationships between FDX1 expression and immune infiltration, immune cells, immune checkpoints, tumor mutation burden (TMB), microsatellite instability (MSI), mismatch repair (MMR), and DNA methyltransferase (DNMT) were explored." (PMID 36825202, 2023). "Meanwhile, Cu2+ tolerance in HepG2 cells with FDX1 knockdown was significantly increased compared with the control group, which suggested that tumor cells with a high FDX1 expression was easier to be caused cuproptosis at the same Cu2+ content." (PMID 37361595, 2023). "FDX1 which expression is significantly lower than normal tissues in a variety of cancer types, is positively correlated with immune cell infiltration and tumor mutation load, and has a clear correlation with tumor survival and prognosis." (PMID 37313458, 2023). "The expression level of FDX1 in ccRCC samples with different ages, gender, pathological tumor stage, histological tumor grade, VHL mutation, and PBRM1 mutation was analyzed." (PMID 36292610, 2022). "Regarding tumour grade, FDX1 was associated with a lower grade in KICH, KIRP, LIHC, and THCA, whereas a higher grade was associated with OV." (PMID 36186457, 2022). "Next, we used the Tumour-Immune System Interaction Database (TISIDB) to investigate the FDX1 association among clinical features across tumours." (PMID 36186457, 2022). "In a previous study, knockdown of FDX1 was found to alter tumor cell metabolism, thereby affecting tumor-associated inflammation and changes in the immune microenvironment." (PMID 36263125, 2022). "Lower FDX1 gene expression levels were strongly associated with higher cancer grades and more advanced tumor–node–metastasis stages." (PMID 36225932, 2022).
tumor (continued). "The results showed that in CGGA database, FDX1 expression was statistically correlated with patient age, tumor grade, chemotherapy resistance, IDH mutation and 1p19q codeletion." (PMID 36523779, 2022). "In the present study, the analysis of parameters such as genomic instability and pathway activity of tumors demonstrated that FDX1 expression was closely associated with tumor biological behavior." (PMID 36226187, 2022). "Subsequently, we explored the association between FDX1 and tumor parameters such as genomic instability, RNA methylation modifications, immune infiltration and pathway activity." (PMID 36226187, 2022). "To further understand the relationship between FDX1 gene mutations and tumor clinical characteristics, we used the cBioPortal platform to analyze the frequency mutations in 33 cancers from the TCGA database." (PMID 36523779, 2022). "The data showed that FDX1 affected well-known tumor-associated pathways in only a small number of tumors." (PMID 36226187, 2022). "We first analyzed the association of FDX1 with multiply pathway activity which play important role in regulating tumor behavior in tumors." (PMID 36226187, 2022). "FDX1 expression positively correlated with tumor mutation burden, neoantigen load, and microsatellite instability scores, highlighting its potential role in tumor immunogenicity." (PMID 40410601, 2025). "In addition, correlation of high FDX1 expression with increased tumor mutation burden, neoantigen load, and microsatellite instability highlights its potential role in enhancing tumor immunogenicity." (PMID 40410601, 2025). "Previous studies have implicated Ferredoxin 1 in modulating various metabolic pathways, including glucose metabolism, lipid metabolism, and mitochondrial function, which are crucial for supporting tumor growth and survival." (PMID 38802900, 2024). "Additionally, FDX1 displayed relationships with the tumor mutational burden (TMB), microsatellite instability (MSI), DNA methylation, and RNA and DNA synthesis (RNAss/DNAss) within the tumor microenvironment." (PMID 37298135, 2023). "FDX1 was differently expressed in most cancer and its expression was associated with immune characteristics and other tumor characteristics including Tumor Mutation Burden (TMB), Microsatellite Instability (MSI), Mismatch Repair (MMR), and DNA methyltransferase (DNMT) in pan-cancer." (PMID 36825202, 2023). "Furthermore, FDX1 expression is closely linked to immune infiltration and predicts a favorable response to the immune checkpoint blockade within the tumor microenvironment." (PMID 37298135, 2023). "Additionally, positive correlations were observed between FDX1 and immune cells infiltration, immune checkpoints, tumor stemness, homologous recombination deficiency (HRD), and TMB in LGG in the pan-cancer analysis." (PMID 36825202, 2023). "We speculated that the change of tumor immune microenvironment might be caused by cuproptosis-induced neoantigen production in patients with HCC with different expression of FDX1." (PMID 37361595, 2023). "Collectively, these data imply that FDX1 expression is positively associated with the CD4+ T cell population and that T cell immune responses may be implicated in FDX1-mediated ccRCC tumor suppression." (PMID 36611966, 2022). "In this study, FDX1 mRNA and protein expression were aberrantly downregulated and associated with ccRCC grade, stage, and nodal metastasis, whereas in adjacent non-tumour kidney tissue, it was abundantly expressed and cytoplasmically localised in renal tubular epithelial cells." (PMID 36186457, 2022). "In addition, HCC patients with a lower expression of FDX1 is associated with shorter survival time probably due to the gain of survival advantage of these tumor cells by resisting against copper-induced toxicity." (PMID 35898502, 2022).
tumor (continued). "More correlation analyses between FDX1 expression and mutational markers, such as tumor mutational burden (TMB) and microsatellite instability (MSI), were also examined via Spearman assay to explore the relation between FDX1 expression and the sensitivity of common antitumor drugs." (PMID 36061184, 2022). "For instance, FDX1 is closely associated with senescence and spontaneous tumor formation in mice." (PMID 36210836, 2022). "To investigate whether FDX1 deficiency affects the growth of tumor cells, we constructed the FDX1-deficient cells using small interference RNA and determined the knockdown efficiency through qPCR." (PMID 34690780, 2021). "This phenomenon may be associated with the elevated expression of FDX1 in tumor tissues." (PMID 41516324, 2025). "In addition, FDX1 expression was positively correlated with the CD4+ T cell population, and the T cell immune response may be associated with FDX1-mediated tumor suppression in ccRCC." (PMID 39482784, 2024). "Moreover, low FDX1 expression was related to shorter survival time and high immune activation, as indicated by alterations in the tumor mutational burden and tumor microenvironment, stronger immune cell infiltration and immunosuppression point expression, and a higher TIDE score." (PMID 37432054, 2023). "FDX1 mRNA and protein expression were aberrantly downregulated and associated with malignant progression and advanced clinicopathological characteristics of ccRCC, whereas in adjacent non-tumour kidney tissue, it was abundantly expressed and cytoplasmically localised in the PCT." (PMID 36186457, 2022). "The mechanism underlying the role of FDX1 in tumour development remains unclear." (PMID 36186457, 2022). "Mechanistic studies confirmed that this formulation specifically accumulates copper ions within tumor cells, upregulates FDX1, promotes DLAT oligomerization, and induces mitochondrial dysfunction, thereby driving copper death." (PMID 41599733, 2026). "At last, it was uncovered that the tumor growth and metastasis were relieved after FDX1 overexpression, but these changes were reversed after EGF treatment." (PMID 38520567, 2025). "Further examination of FDX1 expression in the TNBC patients showed significantly higher expression levels in normal tissues than those in tumor tissues, both in the TCGA database and the database of our center." (PMID 39976173, 2025). "Consistently, immunohistochemistry (IHC) analysis of tumor sections showed elevated FDX1 levels in NUDT21-knockdown xenografts." (PMID 40425546, 2025). "Typically, the released Cu2+ binds to ferredoxin 1 (FDX1) and reduced to Cu+, while ES chelates and transports extracellular Cu2+ into tumor cells, leading to mitochondrial stress and the disruption of cellular energy 25,26." (PMID 40963914, 2025). "Our research conclusions are consistent with these studies, indicating that FDX1 plays an inhibitory role in the initiation and progression of tumor cells." (PMID 40276654, 2025). "Copper accumulation modulates tumor-infiltrating immune cells by regulating cuproptosis-related genes like FDX1 and LIAS, which influence T-cell activity and macrophage polarization to alter immune surveillance." (PMID 41158129, 2025). "This resulted in an increase in intracellular Cu2+ levels, upregulation of FDX1 expression, subsequent induction of cuproptosis, and ultimately resulting in tumor growth inhibition." (PMID 40756352, 2025). "Future research should further elucidate the molecular mechanisms of FDX1 in cuproptosis and explore its potential roles in tumor resistance." (PMID 40406488, 2025). "Specifically, AKT1 inhibited the protein lipoylation by phosphorylating FDX1 while simultaneously regulating tumor metabolic reprogramming, ultimately suppressing cuproptosis." (PMID 39976173, 2025). "In this study, we demonstrate that cuproptosis inhibits OC cell proliferation, migration, and invasion through FDX1 regulation and suppresses tumor growth in a mouse model." (PMID 40119652, 2025).
tumor (continued). "While the WT and S63A mutant FDX1 suppressed tumor progression, the S63D mutant substantially enhanced tumor growth." (PMID 39976173, 2025). "Specifically, AKT1 inhibits protein lipoylation by phosphorylating FDX1 while regulating tumor metabolic reprogramming, ultimately suppressing cuproptosis." (PMID 40406488, 2025). "In summary, our findings provide solid evidence that copper with Elesclomol can induce cuproptosis through FDX1 regulation and significantly inhibit OC tumor progression in vivo and in vitro." (PMID 40119652, 2025). "The current study shows that the copper death-dependent protein ferredoxin (FDX) plays a significant role in HCC: disruption of FDX1 promotes tumor cell proliferation and migration, whereas high expression of FDX2 reduces cell viability in HCC samples." (PMID 40433591, 2025). "Recently, many studies have pointed out that FDX1 is a direct target of copper-dependent cell death and have demonstrated its potential value in tumor therapy." (PMID 40118855, 2025). "The key regulator of cuproptosis, FDX1, can be related to tumor metastasis stages and patient outcomes." (PMID 40064873, 2025). "Given its central role in the mechanisms of cuproptosis, targeting FDX1 holds significant research and clinical potential for anti-tumor resistance strategies." (PMID 40406488, 2025). "Taken together, these data showed that phosphorylated FDX1 promoted the transition from mitochondrial respiration to glycolysis, allowing tumor cells to adapt to rapid growth." (PMID 39976173, 2025). "The tumor size, volume, and weight were all relieved after FDX1 overexpression, but these changes were reversed after EGF treatment (p < 0.001)." (PMID 38520567, 2025). "At last, our results demonstrated that the tumor growth and metastasis were relieved after FDX1 overexpression, but these changes were rescued after EGF treatment." (PMID 38520567, 2025). "The FDX1 expression in tumor cells was also positively related to CD8 T cell proportion and negatively associated with immunosuppressive molecules, which indicates FDX1-involved cuproptosis can trigger the antitumor immunity." (PMID 40064873, 2025). "Conversely, tumor tissues exhibited significantly reduced expression of FDX1, CAT, and EHHADH than normal (p < 0.05)." (PMID 40109870, 2025). "Surprisingly, IDH2R140Q mutation changed the expression patterns of cupropotosis-associated genes, including FDX1, LIAS, LIPT1, DLD, DLAT, and PDHA1, which indicated that the sensitivity of tumor cells to cuproptosis depends on the types of genetic mutations." (PMID 40384935, 2025). "One of novel outcomes of this study is the connotation among FDX1 expression and the tumor immune microenvironment." (PMID 40410601, 2025). "High FDX1 expression correlated with reduced tumor immune microenvironment components, including lower immune, stromal, and ESTIMATE scores." (PMID 40410601, 2025). "In conclusion, for the first time, our work manifested that FDX1 retarded EMT progress to suppress the tumor growth and progression of CRC." (PMID 38520567, 2025). "Our findings highlight FDX1 as a potential tumor suppressor in LUAD, acting through modulation of the GPRIN2/PI3K signaling pathway." (PMID 38802900, 2024). "In the visual circular and hierarchical plots of the VEGF signaling pathway, our analysis revealed VEGFA + tumor/epithelial cells and FDX1 + tumor/epithelial cells had the most significant effect on endothelial cells." (PMID 38200479, 2024). "FDX1, emerging as a formidable tumor suppressor, wielded its influence by curbing the proliferation, migration, and invasion capacities of cancer cells." (PMID 38802900, 2024). "Compared to the normal group, FDX1, a key gene of cuproptosis in the tumor group, was highly methylated, and FDX1 provides electrons to initiate a free radical chain reaction catalyzed by acyl synthetase." (PMID 38573998, 2024).
tumor (continued). "So EREG has immunotherapeutic potential by affecting PD-L1 expression and anti-tumor potential by mediating cuproptosis through affecting FDX1 expression." (PMID 39482784, 2024). "The results showed that FDX1 was significantly down-regulated in tumor tissue compared to normal tissue." (PMID 38938647, 2024). "We observed higher expression of the key gene VEGFA in the VEGFA + tumors/epithelial cells, tumor/epithelial cells, and FDX1 + tumors/epithelial cells in the VEGF signaling pathway." (PMID 38200479, 2024). "In conclusion, the key regulatory gene FDX1 of pos.cu.sig genes can be used as a candidate marker and potential therapeutic targets for tumor immunotherapy prognosis evaluation in KIRC." (PMID 39206152, 2024). "The incorporation of ES into Cu-MOFs nanoplatform has demonstrated potential to induce cuproptosis burst in an FDX1-dependent manner and stimulate tumor cell death in an immunogenic manner, thus improving the survival rate of tumor-bearing mice." (PMID 38938647, 2024). "FDX1 holds promise as a viable biomarker and therapeutic target for assessing the effectiveness of tumor immunotherapy in KIRC." (PMID 39206152, 2024). "Conversely, FDX1 overexpression led to a significant reduction in tumor growth and tumor weight in LUAD cells, an effect that was counteracted by GPRIN2 depletion." (PMID 38802900, 2024). "MiR-21-5p acted as an upstream regulator of FDX1 to drive the development of ccRCC, and promoted the growth and invasive ability of tumor cells by inhibiting FDX1 expression." (PMID 39482784, 2024). "Our results revealed the main outgoing signals of FDX1 + tumor/epithelial cells were PDGF, WNT, CD46, MHC-1, MIF, and MK pathways, while the primary incoming signals were IFN-II and other pathways." (PMID 38200479, 2024). "Due to its important role in tumorigenesis and tumor immunity, FDX1 can serve as a potential therapeutic target and prognostic marker in various malignancies." (PMID 37035162, 2023). "The heatmap indicated that 1p19q codeletion, IDH mutation status, chemotherapy, age, tumor grade, histology, and PRS type differed significantly between the high- and low-FDX1 groups (p < 0.05)." (PMID 37301546, 2023). "Subsequently, we further detected FDX1 expression in healthy and tumor tissues by immunohistochemistry based on the HPA database." (PMID 37298135, 2023). "In KIRC-TCGA database, the expression of FDX1 was decreased in tumor tissues compared with adjacent tissues (p < .05)." (PMID 36755576, 2023). "As for protein level, NDUFS1 and FDX1 was also positively correlative with the correlation coefficient in tumor was only 0.40 while in adjacent normal tissues was 0.82, which was consisting with the trend between the difference in NDUFS1 mRNA and protein." (PMID 37469574, 2023). "FDX1 had a close correlation to the signatures of immunotherapy prediction including immune checkpoints, tumor stemness, HRD, and TMB, which demonstrated its potential role as an immunotherapy predictor." (PMID 36825202, 2023). "This study reveals that cuproptosis and tumor immune microenvironment were together involved in improvement of survival in patients with HCC with a high expression of FDX1." (PMID 37361595, 2023). "The tumor stemness analysis demonstrated the correlation between FDX1 and the DNAss/RNAss value; we also found a positive relationship between FDX1 and SKCM and STAD." (PMID 37298135, 2023). "The FDX1 expression in paired and unpaired tumor samples illustrated that the FDX1 downregulated compared with normal kidney tissues (p < .05)." (PMID 36755576, 2023). "The xenograft tumor model indicated that FDX1 OE significantly inhibited the growth of UCEC and attenuated the PCNA, HK2, PKM2, and Ki-67 expression." (PMID 37945610, 2023). "The expression level of FDX1 was lower in ccRCC tumor tissues, and the total copper death enrichment scores were also decreased in tumor tissues." (PMID 36766692, 2023).